TRMT9B (tRNA methyltransferase 9B (putative))
Description:
May modify wobble uridines in specific arginine and glutamic acid tRNAs. Acts as a tumor suppressor by promoting the expression of LIN9.
Synonyms: C8orf79; KIAA1456; TRM9L; FLJ36980; hTRM9L
Tractability: PROTAC: ubiquitination databases record sites on it.
Gene: Protein-coding gene on chromosome 8 (12,945,642 to 13,031,503, forward strand). Ensembl gene ENSG00000250305.
Subcellular location (Human Protein Atlas): Nucleoplasm; Cytosol
Pathways (Reactome):
Metabolism of RNA: tRNA modification in the nucleus and cytosol
Gene Ontology:
Molecular function: tRNA methyltransferase activity; tRNA (5-carboxymethyluridine(34)-5-O)-methyltransferase activity; tRNA binding; S-adenosylmethionine-dependent methyltransferase activity
Biological process: tRNA methylation; tRNA modification
Cellular component: cytoplasm; nucleus
Genetic constraint (gnomAD): Loss-of-function variants: 21 observed, 15.29 expected, observed/expected ratio (o/e) 1.37, 90% interval 0.97 to 1.86. The synonymous counts are far from expectation, so gnomAD's model fits this gene poorly and the ratio says little. Missense variants: 923 observed, 569.78 expected, observed/expected ratio (o/e) 1.62, 90% interval 1.53 to 1.71. Synonymous variants: 270 observed, 200.27 expected, observed/expected ratio (o/e) 1.35, 90% interval 1.22 to 1.49.
Homologues: Orthologues: chimpanzee TRMT9B (98% identical), macaque TRMT9B (94% identical), dog TRMT9B (82% identical), pig TRMT9B (80% identical), rabbit TRMT9B (77% identical), guinea pig TRMT9B (75% identical), mouse Trmt9b (73% identical), rat Trmt9b (73% identical), tropical clawed frog trmt9b (50% identical). Paralogues in human: ALKBH8 (26% identical), ALKBH6 (5% identical).
Diseases named in the same sentence as TRMT9B in open-access papers:
TRMT9B is named in the same sentence as 13 diseases in open-access papers, as found by Europe PMC text mining. Sharing a sentence is not in itself a finding about the gene and the disease. The quoted sentences say what the papers report.
breast carcinoma (2 papers, 2012 to 2021). "tRNA methyltransferase 9B (TRM9L/TRMT9B) has been shown to be downregulated in breast cancer." (PMID 34827123, 2021).
myeloma (1 paper, 2020). "In addition to translocation and myeloma subgroups, we found novel active domains, for instance, proximal to CCND2 and TRMT9B in MMSET patients." (PMID 33138842, 2020).
tumor (11 papers, 2012 to 2026). "The discovery of TRMT9B as a novel regulatory factor in synaptic formation underscores its potential significance beyond tumor suppression." (PMID 39061374, 2024).
TRMT9B also shares sentences with these, for which no sentence is quoted: cancer (3 papers); ovarian carcinoma (3); colon carcinoma (2); lung carcinoma (2); benign ovarian tumor (1); benign tumor (1); bladder carcinomas (1); colorectal cancer (1); colorectal tumour (1); infection (1).